VNN3P (vanin 3, pseudogene)
Synonyms: HSA238982; formerly VNN3
Gene: Transcribed unitary pseudogene on chromosome 6 (132,722,926 to 132,734,692, reverse strand). Ensembl gene ENSG00000093134.
Genetic constraint (gnomAD): Loss-of-function variants: 15 observed, 20.37 expected, observed/expected ratio (o/e) 0.74, 90% interval 0.49 to 1.13. The upper end of that interval is the gene's LOEUF score, 1.13, which puts it in group 4 of 6, group 1 being the genes least tolerant of losing a copy. Missense variants: 338 observed, 317.59 expected, observed/expected ratio (o/e) 1.06, 90% interval 0.97 to 1.16. Synonymous variants: 122 observed, 117.55 expected, observed/expected ratio (o/e) 1.04, 90% interval 0.89 to 1.21.